GPR68 (G protein-coupled receptor 68)
Diseases named in the same sentence as GPR68 in open-access papers (continued):
Sharing a sentence is not in itself a finding about the gene and the disease.
tumor (continued). "Unfortunately, other than its expression in tumour cell lines or in animal models, little is known about the presence of GPR68 in human tumour samples." (PMID 31652823, 2019). "The numerous tumors with increase in expression of GPR68 suggest its potential relevance in tumor biology and as a potential therapeutic target in multiple cancers." (PMID 30696114, 2019). "GPR68 expression increases early in tumor development and is highly prevalent in both male and female PDAC patients." (PMID 30696114, 2019). "Often, only small areas with strong staining were observed, whereas large regions of the tumours were completely devoid of any GPR68 expression, thus leading to a low overall rating (IRS values)." (PMID 31652823, 2019). "Targeting tumor acidity can suppress tumor growth, which further supports the idea that GPR68 is an attractive target for anti-cancer drug development, perhaps as part of combination therapeutic regimens." (PMID 30696114, 2019). "Although expression of GPR68 has been described in many tumour cell lines, little is known about its presence in human tumour entities." (PMID 31652823, 2019). "GPR68 (OGR1) belongs to the proton-sensing G protein-coupled receptors that are involved in cellular adaptations to pH changes during tumour development." (PMID 31652823, 2019). "A number of cancer cell lines show substantial GPR68 expression but several tumor types with elevated expression of GPR68 in tumors have only modest magnitudes of GPR68 expression in the cancer cells." (PMID 30696114, 2019). "Further work is needed to resolve the apparently opposing roles of GPR68 in tumor cells and host cells." (PMID 30696114, 2019). "The novel antibody 16H23L16 will be a valuable tool for basic research and for identifying GPR68-expressing tumours during histopathological examinations." (PMID 31652823, 2019). "Together, these data suggest that GPR68 expression in myeloid lineage cells has a role in tumor cell-induced immunosuppression." (PMID 30696114, 2019). "This high expression may be closely related to tumor development, possibly due to the involvement of GPR68 in the interaction between tumor cells and the tumor microenvironment." (PMID 41190345, 2025). "Tumor studies have shown that GPR68 may regulate immune cells through cytokines/inflammatory factors and thus affect tumor progression and initiation." (PMID 41190345, 2025). "GPR68 is expressed in macrophages, and the activation of GPR68 may lead to the polarization of macrophages into the M2 phenotype, which usually has immunosuppressive properties and contributes to tumor growth and metastasis." (PMID 41190345, 2025). "The role of GPR68 may vary across different tumors, potentially inhibiting tumor growth or promoting its progression." (PMID 41190345, 2025). "Activation of GPR68 may inhibit the activity of some immune cells, thus providing good conditions for the immune escape of tumor cells and the occurrence and development of tumors." (PMID 41190345, 2025). "Besides its roles in cancer cells, studies have demonstrated that GPR68 plays an important role in tumor immune cells and fibroblasts." (PMID 39336742, 2024). "Other studies have shown that GPR68 expression in non-tumor cells can promote carcinogenesis." (PMID 36611126, 2023). "The presence of acid and mechanical stimulation is considered a defining hallmark of the tumor microenvironment (TME), and GPR68 could play a critical role in this setting." (PMID 37350933, 2023). "Furthermore, GPR68 functionally inhibits the expression of IFNγ in the tumor infiltrating CD8+ T cells and NK cells as well as the inflammatory cytokine expression in the spleen in male mice but not in females." (PMID 37350933, 2023). "The complex roles for GPR68 may be attributed to the tumor type, stage of cancer and role of non-tumor cells (stromal, endothelial, immune)." (PMID 36611126, 2023).
tumor (continued). "This is consistent with tumor volume being low only in Gpr68-/- male mice, suggesting the tumor-suppressing phenotype in male Gpr68-/- mice could be mostly due to higher IFNγ expression in NK cells, but not other cell types." (PMID 37350933, 2023). "Our results show that Gpr68 could be a potential target to enhance immunity in tumor microenvironment in males." (PMID 37350933, 2023). "Gpr68-/- male mice showed enhanced CD8+ T cell infiltration in the B16-F10 cell tumor, suggesting that GPR68 may have a tumor-promoting role in host cells." (PMID 37350933, 2023). "In addition, activation of GPR68 caused the stimulation and secretion of proinflammatory mediators such as IL‐6 and IL‐8 (CXCL8), which triggered tumor progression." (PMID 35311103, 2022). "In addition, GPR68 is associated with tumor suppressor and MAFB is associated with proto-oncogene and tumor suppressor activities." (PMID 34715892, 2021). "Additionally, higher GPR68 expression was noted in well-differentiated tumours than in highly aggressive neoplasms with high Ki-67 values and with lymph node metastases already present at diagnosis." (PMID 31652823, 2019). "Often, tumour capillaries were also strongly GPR68-positive." (PMID 31652823, 2019). "Emerging evidence implies that GPR68 has key roles in tumor biology." (PMID 30696114, 2019). "However, the overall intensity of GPR68 expression in the human tumour entities and in the cell lines was relatively low." (PMID 31652823, 2019). "Also here, Kaplan–Meier analysis revealed a slightly better outcome for GPR68-positive tumour cases (log-rank test: p = 0.140)." (PMID 31652823, 2019). "Few reports of GPR68 expression in human tumours have been published to date." (PMID 31652823, 2019). "Thus, the present study comprehensively examined GPR68 expression in a broad range of human tumour entities." (PMID 31652823, 2019). "Emerging evidence has revealed that GPR68 may play crucial roles in tumor biology, including tumorigenesis, tumor growth, and metastasis." (PMID 30696114, 2019). "Of note, 12 tumor subtypes have >2-fold increases in GPR68 expression." (PMID 30696114, 2019). "Studies have shown that GPR68 can act as either a tumour suppressor or a tumour promoter." (PMID 31652823, 2019). "Notably, GPR68 expression in the tumour samples displayed substantial inter- and intra-individual variability." (PMID 31652823, 2019). "Furthermore, co-injection of WT macrophages with tumor cells increased TRAMP-C2 tumorigenesis in GPR68 KO mice." (PMID 30696114, 2019). "Knock-out studies in mice implicate Gpr68 with osteoclastogenesis and tumor formation." (PMID 25551770, 2014). "However, a direct role of GPR68 in tumor cells remained unexplored." (PMID 38291540, 2024). "Furthermore, GPR68 may play a crucial role in tumor biology, including tumorigenesis, tumor growth, and metastasis." (PMID 36902589, 2023). "Cancer-associated fibroblasts (CAFs) are responsible for a dense fibrotic tumor stroma, and an increased expression of GPR68 could be shown in CAFs, resulting in enhanced interleukin-6 (IL-6) expression via a cAMP/PKA/cAMP response element-binding protein signaling pathway." (PMID 36902589, 2023). "However, the same study shows that the expression of GPR68 in fibroblasts promotes the formation of tumor spheroids by human colorectal carcinoma cells (HCT116) in vitro, and the same occurs with the in vivo growing of cells from human metastatic breast carcinoma (MDA-MB-453) in nude mice." (PMID 33113952, 2020). "Hence, the impact of GPR68 may vary depending on the tumour cell type, microenvironment, and there may be differences in the effects on primary tumors and metastases." (PMID 31652823, 2019). "Therefore, indirect targeting of these tumours via GPR68 expressed in the tumour stroma may also represent a promising therapeutic strategy." (PMID 31652823, 2019). "Thus, in these latter experiments, GPR68 acted as a tumour promoter." (PMID 31652823, 2019).
tumor (continued). "In addition, tumor weights and volumes were reduced in GPR68 KO mice compared to WT mice." (PMID 30696114, 2019). "GPR68 may be expressed in a variety of cell types in the TME besides tumor cells themselves." (PMID 30696114, 2019). "Knockout of G protein-coupled receptor 68 (GPR68) or inhibition of the IL-6/STAT3 pathway in MSCs has been shown to suppress in situ OS growth and extend the lifespan after tumor xenograft transplantation." (PMID 40600065, 2025). "One study used OGM, a novel small molecule inhibitor of GPR68, to explore the role of GPR68 in GBM cells and found that blocking the GPR68 signaling pathway led to ferroptosis of tumor cells in GBM cell lines." (PMID 41190345, 2025). "For example, in GBM, a novel small molecule drug, OGM, inhibits GPR68 by activating ATF4, which induces ferroptosis and inhibits tumor progression." (PMID 41190345, 2025). "There also seems to be a positive correlation between the acidic tumor microenvironment of GBM and GPR68 expression." (PMID 39336742, 2024). "However, whether GPR68 is involved in gender-dependent regulation of tumor growth is unclear." (PMID 37350933, 2023). "Of course, future studies will be required to better explain these results and to clarify the mechanistic functions of ALPL, GPR68, NETO1, and VGF in the GBM TME and how they can mediate the success of CW application in the tumor resection cavity." (PMID 35884475, 2022). "An increased number of tumor infiltrating T cells was found in subcutaneous prostate tumors from GPR68 KO mice; depleting CD4 or CD8 T cells led to tumor rejection." (PMID 30696114, 2019). "We validated these data at the protein level and discovered that GPR68 mediates symbiotic crosstalk between CAFs and PDAC cells and contributes to the tumor phenotype." (PMID 31765370, 2019). "GPR68 knockout reactivated CD8+ cytotoxic T cells and enhanced the anti-tumor responses." (PMID 39336742, 2024). "We’ve shown that female mice, regardless of genotype, have similar CD8+ T lymphocyte and NK cell infiltration levels compared to Gpr68-/- male mice, yet the tumor growth is not affected." (PMID 37350933, 2023). "Independent of tumour cells, capillaries, granulocytes, and macrophages within some tumours were strongly GPR68-positive." (PMID 31652823, 2019). "Adoptive transfer of differentiation (CD)11b+/Gr1 (Ly-6G/Ly6-C)+ double positive cells isolated from WT, but not from GPR68 KO, mice were necessary and sufficient for tumor development in GPR68 KO mice." (PMID 30696114, 2019). "Accordingly, Kaplan–Meier analysis revealed a slightly better outcome for patients with GPR68-positive tumours (IRS ≥ 3) compared to those with GPR68-negative neoplasms (log-rank test: p = 0.104)." (PMID 31652823, 2019). "myCAFs are located in CAFs adjacent to tumor cells, while iCAFs marked by PDPN and/or COL14A1 are distant from tumor cells, where hypoxic and acidic environments being located in iCAFs putatively due to poor blood supply is consistent with HIF1A and GPR68 expressions." (PMID 38892190, 2024). "In the intricate landscape of the tumor microenvironment, the signal transduction triggered by lactate stimulation mainly relays on the lactate receptor HCAR1 (GPR81), and proton-sensing G-protein coupled receptors (GPRs), including GPR4, TDAG8 (GPR65), OGR1 (GPR68), and G2A (GPR132)." (PMID 38576043, 2024). "However, the role of tumor microenvironment acidification in GPR68 activation has not been assessed in cancer." (PMID 38291540, 2024). "Since GPR68 expressed in tumor cells have no direct impact on melanocyte migration and proliferation, it is highly plausible that the tumor microenvironment or the immune system has a determining effect on tumor growth in vivo." (PMID 37350933, 2023).
tumor (continued). "The highest expressed GPCRs in PDAC tumors (as an example, this finding is generalizable to other tumor types) are generally overexpressed compared to normal tissue and include orphan receptors (e.g., GPRC5A and ADGRF4/GPR115) and GPCRs with known agonists (e.g., GPR68)." (PMID 31765370, 2019). "Furthermore, relevant studies have shown that GPR68 functionally inhibits the expression of IFN-γ in tumor-infiltrating CD8+ T cells and NK cells, which may lead to tumor immune escape and further promote tumor growth." (PMID 41190345, 2025). "However, in these experiments, no influence of GPR68 on primary tumour growth was observed." (PMID 31652823, 2019). "However, Kaplan–Meier analysis could not demonstrate statistically significant differences between patients with GPR68-positive or -negative tumours, likely due to too few positive cases (log-rank test: 0.465)." (PMID 31652823, 2019). "In the absence of extracellular acidosis, the activation of GPR68 in MCF7 and T47D cells using Ogerin also increased the formation of cytoplasmic lipid droplets, indicating that GPR68 may be responsible for this cellular adaptation to the acidic tumor microenvironment." (PMID 39336742, 2024).
cancer (41 papers, 2009 to 2026). A tumor composed of atypical neoplastic, often pleomorphic cells that invade other tissues. "In cancer-associated fibroblasts, acidic activation of GPR68 promotes IL-6 expression via a cAMP-PKA-CREB pathway." (PMID 41595528, 2026). "GPR68 is expressed in cancer-associated fibroblasts (CAFs) and immune cells and serves a pivotal function in a variety of diseases by regulating cytokine production." (PMID 41190345, 2025). "Usage of Lorazepam, which has off target agonism of GPR68, is linked to worse clinical outcomes for a variety of cancers." (PMID 38291540, 2024). "Future studies should focus on revealing the specific mechanisms underlying the effects of GPR68 and its role in chronic inflammation and different types of cancer to develop more effective treatment strategies for improving patient survival and quality of life." (PMID 41190345, 2025). "Studies have revealed crucial roles of GPR68 in cancer-associated fibroblasts (CAFs) as well." (PMID 39336742, 2024). "MAFB and GPR68 genes are downregulated interactors of RFX6 that Swiss-Prot associates with cancer." (PMID 34715892, 2021). "GPR68 somatic mutations are extremely rare in human cancers." (PMID 30696114, 2019). "Although substantial progress has been made in characterizing GPR68 as a proton-sensing receptor in inflammation, cancer, and stromal biology, several key gaps limit the translation of these findings into the OA field." (PMID 41595528, 2026). "In cancer models, GPR68 activation can support survival pathways, while its inhibition enhances cell death and immune responsiveness." (PMID 41595528, 2026). "The expression of GPR68 is highly upregulated in several cancer types, including different histological subtypes of NSCLC." (PMID 40061137, 2025). "In summary, GPR68 is a potential therapeutic target for inflammatory diseases, cancer, fibrosis, and age-related decline in hematopoietic function." (PMID 41190345, 2025). "GPR68 is involved in the pathogenesis of a variety of aging-related diseases, including inflammatory diseases and cancer." (PMID 41190345, 2025). "GPR68 expression is markedly increased in multiple tumors and correlates with poor patient prognosis, implying that GPR68 is a potential prognostic marker for cancer." (PMID 41190345, 2025). "Herein, we review the current research progress pertaining to these proton-sensing GPCRs, including GPR4, GPR65 (TDAG8), and GPR68 (OGR1), in inflammation and cancer." (PMID 39336742, 2024). "Cytoskeleton remodeling and the G12/13-Rho-Rac1 pathway were indicated in the GPR68-mediated inhibition of cancer cell migration." (PMID 39336742, 2024). "In parallel to this discovery, investigations into the development of new agonists and antagonists have been conducted in efforts to support a better understanding of the biology behind GPR68’s function in inflammation and cancer biology." (PMID 39336742, 2024). "This is the first study on pH-GPCRs in peritoneal carcinomatosis, which shows lower expression of GPR4 and GPR68 as compared to other pH-GPCRs in this type of cancer." (PMID 36902589, 2023). "In order to assess the effect and mechanism of GPR68 in BC, four cell lines were selected as they showed various GPR68 expression according to the EBI tool using RNA-seq data of cancer cell line encyclopedia." (PMID 35311103, 2022). "Since BC is the most prevalent cancer globally, we aimed at investigating the expression pattern of GPR68 in order to understand its role in the BC microenvironment." (PMID 35311103, 2022). "The TNMplot tool explored the GPR68 expression in various cancer types, where BC was among the tumors with a significant differential expression." (PMID 35311103, 2022). "The transformation of MSCs into cancer-associated fibroblasts CAFs is postulated to result from decreased ECM pH and is further dependent on GPR68 and its downstream effectors, G-protein-coupled receptor (GPCR) and YAP." (PMID 34681692, 2021).